CAST (calpastatin)
Description:
Specific inhibition of calpain (calcium-dependent cysteine protease). Plays a key role in postmortem tenderization of meat and have been proposed to be involved in muscle protein degradation in living tissue.
Synonyms: formerly MIR583HG
Gene: Long non-coding RNA gene on chromosome 5 (95,962,001 to 96,631,085, forward strand). Ensembl gene ENSG00000153113.
Subcellular location (Human Protein Atlas): Cytosol; Endoplasmic reticulum; Plasma membrane
Pathways (Reactome):
Disease: Deregulated CDK5 triggers multiple neurodegenerative pathways in Alzheimer's disease models
Extracellular matrix organization: Degradation of the extracellular matrix
Genetic constraint (gnomAD): Loss-of-function variants: 15 observed, 19.12 expected, observed/expected ratio (o/e) 0.78, 90% interval 0.52 to 1.21. The upper end of that interval is the gene's LOEUF score, 1.21, which puts it in group 5 of 6, group 1 being the genes least tolerant of losing a copy. Missense variants: 283 observed, 262.54 expected, observed/expected ratio (o/e) 1.08, 90% interval 0.98 to 1.19. Synonymous variants: 100 observed, 95.85 expected, observed/expected ratio (o/e) 1.04, 90% interval 0.89 to 1.23.
Diseases named in the same sentence as CAST in open-access papers:
CAST is named in the same sentence as 149 diseases in open-access papers, as found by Europe PMC text mining. Sharing a sentence is not in itself a finding about the gene and the disease. The quoted sentences say what the papers report.
Obesity (9 papers, 2006 to 2025). Accumulation of substantial excess body fat. "Among them, genes of the glucose metabolism, such as CAPN10, encoding for calpain, a calcium-sensitive cysteine protease associated with type 2 diabetes, and its inhibitor CAST, involved in obesity-induced AT inflammation, were up-regulated in this subject group." (PMID 30838002, 2019). "Despite that this method has not been used elsewhere and the lack of alternative methods for subcongenic strains, the results obtained by this approach suggest further investigation of the “Gnas imprinted locus” and the effects that CAST alleles have on obesity at this locus." (PMID 25613955, 2015). "To investigate the role of calpains in diet-induced obesity, we used CAST overexpressing transgenic mice to inhibit activities of both calpain-1 and -2." (PMID 29089532, 2017). "CAST overexpression significantly attenuated obesity-induced inflammatory responses in adipose tissue." (PMID 29089532, 2017). "Using CAST transgenic mice, we examined the role of calpains in adipose tissue remodeling during diet induced-obesity." (PMID 29089532, 2017). "Further studies are warranted to understand the mechanisms by which (i) calpain activation promotes PCK-1 gene expression and activity and (ii) CAST overexpression leads to insulin resistance in long term obesity." (PMID 29089532, 2017). "CAST Tg overexpression mediated calpain inhibition significantly suppressed obesity induced apoptotic cell death, pro-apoptotic genes (Bid, Bax, and Bcl10), and adipose tissue macrophage accumulation." (PMID 29089532, 2017). "Growth and meat quality traits were evident through CAST (calpastatin, regulating muscle tenderness), FTO (fat mass and obesity‐associated gene, impacting fat deposition), GHR (growth hormone receptor) and MTOR (mechanistic target of rapamycin, controlling muscle protein synthesis)." (PMID 40859468, 2025). "In the Ossabaw swine model of obesity there was an up-regulation of 186 PVAT-derived proteins associated with increased coronary contractility and these included transforming protein RhoA and calpastatin." (PMID 29479319, 2018). "The same study also reported that obesity leads to a dysregulation of calpastatin." (PMID 29234017, 2017). "The observed reduction in adipocyte apoptosis, in addition to, impaired macrophage migration, and accumulation upon CAST overexpression may well correlate with the observed reduction of obesity-induced adipose tissue inflammation." (PMID 29089532, 2017). "Interestingly, CAST overexpression showed a slight and significant improvement in the early stage (5 weeks) of obesity, which disappeared in the late stage of obesity (16 weeks)." (PMID 29089532, 2017). "To examine the effect of CAST overexpression on HFD-induced glucose tolerance, we performed glucose tolerance test (GTT) and insulin tolerance test (ITT) during an early (5 or 6 weeks post diet) and late (15 or 16 weeks post diet) stage of obesity." (PMID 29089532, 2017). "However, since numerous obesity QTL have been found on MMU2, some of which were discovered in B6 by CAST crosses, we chose to measure dissected fat pad weights as a more sensitive measure of adiposity." (PMID 16670015, 2006). "In addition, QTLs for obesity and related traits identified from CAST/EiJ and other strains have so far not been fine-mapped to the Pbwg1.5 region on mouse chromosome 2." (PMID 25398139, 2014).
breast carcinoma (7 papers, 2012 to 2025). "To elucidate the mechanisms underlying TXNIP’s antitumor effects in breast cancer cells, we conducted co-immunoprecipitation and proteomic analyses that revealed calpastatin (CAST) as a novel TXNIP-interacting protein in MDA-MB-231 and HCC-1954 cells." (PMID 40175348, 2025). "In inflammatory cases, high calpain-1 and high calpastatin expression is associated with improved breast cancer-specific survival." (PMID 27323818, 2016). "Low calpastatin expression was significantly associated with adverse breast cancer-specific survival of the inflammatory breast cancer patients (P=0.020), as was low calpain-1 expression (P=0.003)." (PMID 27323818, 2016). "An association between low cytoplasmic calpastatin expression and the presence of lymphovascular invasion, encompassing invasion of both lymphatic and blood vessels has been reported in breast cancer." (PMID 23140395, 2012). "While high calpain-2 and low CAST expression was associated with improved survival in patients with non-inflammatory breast cancer treated with neoadjuvant chemotherapy, high calpain-1 and high CAST expression in the inflammatory group was associated with improved breast cancer survival." (PMID 37795261, 2023). "High caspase-3/high calpain-1, high caspase-3/high calpain-2 and high caspase-3/low calpastatin expression significantly associated with adverse breast cancer-specific survival in the total patient cohort; and combinational caspase-3/calpain-1 has important prognostic value in basal-like patients." (PMID 27798717, 2017). "Furthermore, low expression of calpastatin and calpain-1 is significantly associated with adverse breast cancer-specific survival in inflammatory large but operable primary breast cancer." (PMID 27323818, 2016). "Furthermore, low calpain-1 and calpastatin expression are associated with adverse survival of patients with inflammatory large but operable breast cancer." (PMID 27323818, 2016). "The expression of calpain-1, calpain-2 and calpastatin was determined in diagnostic core biopsy samples taken from patients with large but operable breast cancer or locally advanced breast cancer who subsequently received neoadjuvant chemotherapy prior to surgical resection." (PMID 27323818, 2016). "The aim of this study was to investigate the expression of calpain-1, calpain-2 and calpastatin in diagnostic, core biopsy specimens from women with large but operable primary breast cancer who were subsequently treated with neoadjuvant chemotherapy prior to surgical excision of residual tumour." (PMID 27323818, 2016). "Conversely, in breast cancer patients, CAST mRNA and protein levels show an inverse relationship with the poor prognostic indicator of lymphovascular invasion, indicating possible anti-tumor activity." (PMID 40175348, 2025). "Only caspase-3/calpastatin expression was identified as an independent factor for breast cancer-specific survival from multivariate analysis." (PMID 27798717, 2017). "The significance of caspase-3/calpastatin for breast cancer-specific survival was retained in multivariate analysis (HR 1.241, 95% CI 1.053–1.462; P = 0.01), when considering previous confounding factors." (PMID 27798717, 2017). "The calpain system in general has been implicated in tumour progression, including altering cellular migration, survival and apoptosis; and expression of calpain-1, calpain-2 and calpastatin have been shown to be important in breast cancer." (PMID 25539577, 2014). "Altered expression of the catalytic subunits of μ-calpain and m-calpain, and calpastatin has been described in a number of tumour types including breast cancer." (PMID 23140395, 2012). "Might the subcellular localization of calpain isoforms, instead of the expression levels of calpains or calpastatin, have a prognosis value in breast cancer?" (PMID 37795261, 2023).
breast carcinoma (continued). "Patients with high caspase-3/high calpain-1 expression, high caspase-3/high calpain-2 expression, high caspase-3/low calpastatin expression, or high caspase-8/low calpain-1 expression had significantly worse breast cancer-specific survival (P = 0.005, 0.049, 0.02, and 0.02 respectively)." (PMID 27798717, 2017). "In conclusion, high calpain-2 and low calpastatin expression is associated with improved breast cancer-specific survival in non-inflammatory large but operable primary breast cancer treated with neoadjuvant chemotherapy." (PMID 27323818, 2016). "This study has demonstrated that low expression of calpain-2 and high expression of calpastatin determined in diagnostic core biopsy samples is significantly associated with adverse breast cancer-specific survival in non-inflammatory large but operable primary breast cancer." (PMID 27323818, 2016). "In addition to identifying the novel interaction between CAST and TXNIP, our study revealed that overexpressing TXNIP increases IL-24 levels while knocking down TXNIP decreases IL-24 expression in breast cancer cells." (PMID 40175348, 2025). "The expression of calpain-1, calpain-2 and calpastatin was determined using immunohistochemistry on core biopsy samples, in a cohort of large but operable inflammatory and non-inflammatory primary breast cancer patients treated with neoadjuvant chemotherapy." (PMID 27323818, 2016). "It is interesting to note that the current results show a high frequency of calpastatin expression within the nucleus, that has not previously been observed in other tumour types, such as breast cancer." (PMID 23140395, 2012).
Alzheimer disease (6 papers, 2008 to 2024). A progressive, neurodegenerative disease characterized by loss of function and death of nerve cells in several areas of the brain leading to loss of cognitive function such as memory and language. "Damaging calpain overactivation has been associated with the pathogenic reduction of the natural endogenous calpain inhibitor calpastatin in vivo models of Alzheimer’s disease, amyotrophic lateral sclerosis and Huntington’s disease." (PMID 35126465, 2021). "By contrast an increase in calpain in Alzheimer's disease brain, the calpastatin expression is markedly reduced in the neocortex in Alzheimer's disease." (PMID 18706097, 2008). "Further, previous studies have demonstrated an inverse correlation between calpain and calpastatin expression levels in the brain of Tg2576, a mouse model of Alzheimer's disease." (PMID 18706097, 2008).
cardiac hypertrophy (6 papers, 2013 to 2025). "It has been reported that transgenic over-expression of CAST significantly attenuated angiotensin II-induced myocardial hypertrophy, diabetes-related myocardial hypertrophy and fibrosis and endotoxaemia-induced myocardial dysfunction." (PMID 25786109, 2015). "Providing further evidence of calpain contribution to myocardial remodeling, the inhibition of calpain by deletion of Capn4 prevented hypertrophy in a model of pulmonary hypertension, and calpastatin overexpression reduced myocardial hypertrophy and fibrosis in a mouse model of type 1 diabetes." (PMID 35456920, 2022). "Several preclinical studies using transgenic models with an altered calpain/calpastatin system and pharmacological inhibitors support the contribution of calpains to the development of cardiac hypertrophy and its progression to adverse remodeling and cardiac dysfunction." (PMID 35456920, 2022). "By contrast, inhibition of calpain by using the same calpastatin overexpressing mouse strain prevented cardiac hypertrophy induced by chronic infusion of angiotensin II through a mechanism independent of NFAT activation but dependent on the translocation to the nucleus of NF-κB." (PMID 35456920, 2022). "Moreover, some of these genes, including the ones coding for catalase and calpastatin, have been involved in the development of cardiac hypertrophy and could therefore provide the link between Cavβ2 expression and this pathology." (PMID 34307509, 2021). "Consistent with this scenario, the attenuation of calpain activity by constitutive calpastatin overexpression or Capn4 genetic deletion reduced the activation of the NFAT pathway and attenuated myocardial hypertrophy in a mouse model of type 1 diabetes." (PMID 35456920, 2022). "In CAST OE mice, basal phenotype and AngII-induced myocardial hypertrophy were comparable with non-induced controls (mean heart to body weight ratios ± SD in milligrams per gram: CAST OE, 4.8 ± 0.4; CAST OE + AngII, 7.1 ± 0.5; non-induced, 4.9 ± 0.4; non-induced + AngII, 7.2 ± 0.4)." (PMID 40025327, 2025). "Globally, these studies demonstrate that calpain overactivation is a general trait of myocardial hypertrophy, regardless of the triggering stimulus, and it is a consequence of calpain overexpression, altered cellular Ca2+ dynamics, and/or reduced calpastatin inhibitory capacity." (PMID 35456920, 2022).
neuroblastoma (5 papers, 2013 to 2025). Neuroblastoma (NB) is the most common solid, extracranial childhood tumor. "Here, the effect of 8-hydroxyquinoline and derivatives (5-chloro-7-iodo-8-hydroxyquinoline or clioquinol and 8-hydroxy-5-nitroquinoline or nitroxoline) on calpain-dependent (calpain-calpastatin) pathways in human neuroblastoma (SH-SY5Y) cells was investigated." (PMID 27635352, 2016). "Altered expression levels for both calpain and calpastatin proteins were also described during human neuroblastoma cell differentiation to Schwann and neuronal cells." (PMID 23717474, 2013). "In neuroblastoma cells treated with H2O2, calpastatin is able to alleviate disturbances in mitochondrial dynamics by decreasing mitochondrial fission protein (Fis-1 and Drp-1) levels." (PMID 34365571, 2022). "In the neuroblastoma cells SH-SY5Y, an upregulation of calpastatin was reported to result in the inhibition of calpain, a proteolytic enzyme involved in many biological processes including migration." (PMID 28418857, 2017). "Consistent with our observations in MYCN-amplified neuroblastoma cells, the cytotoxic effects of Cas9D10A targeting an amplified locus were significantly reduced at many doses in the presence of PARP inhibitors or calpastatin." (PMID 40456709, 2025). "Finally, we assessed whether the cellular toxicity of Cas9D10A-induced DNA damage could be attenuated in the same manner as the MYCN-amplified neuroblastoma cell lines by treating BT-474, NCI-H716, or NCI-H2170 cells with either rucaparib (PARPi) or calpastatin (CAST) in the presence of Cas9D10A." (PMID 40456709, 2025).
retinal degeneration (5 papers, 2012 to 2023). Degeneration of the retina. "CAST/EiJ and NOD.NOH-H2nb1 genetic backgrounds also confer resistance to rd7 associated retinal degeneration; however, genetic modifiers on these backgrounds mapped to independent chromosomal locations." (PMID 24498227, 2014). "Our findings are consistent with the original characterisation of Crb1RD8/RD8 mice, which demonstrated that the retinal degeneration is strongly modulated by backcrosses into C57Bl/6, CAST/EiJ or C3HfB6/Ga mice." (PMID 22545116, 2012). "Ectopic ribbon synapses in the ONL have been observed in a mouse model of retinitis pigmentosa, as well as in a number of mutant mouse lines, including the CAST KO and LKB1 cKO, suggesting an association of these aberrant structures with retinal degeneration and visual defects." (PMID 37108413, 2023). "Specifically, complete suppression of rd7 retinal degeneration was observed in outcrosses of B6.Cg-Nr2e3rd7/rd7 mice to AKR/J, CAST/EiJ or NOD.NOH-H2nb1 mice and several modifier loci that were unique for each strain were identified." (PMID 24498227, 2014). "In S334ter and P23H RHO rats, strong activation of calpain and poly(ADP-ribose) polymerase (PARP), concomitant with calpastatin downregulation, increased oxidative DNA damage and accumulation of PAR polymers was strictly correlated with the temporal progression of retinal degeneration." (PMID 24378535, 2014).
glioblastoma (4 papers, 2018 to 2024). The most malignant astrocytic tumor (WHO grade IV). "CAST promotes GC cell responses to 5‐fluorouracil by regulating the thymidylate synthase‐5‐fluoro‐dUMP complex, but promotes radiation resistance in Glioblastoma multiforme cells by enhancing activity of calpain proteases." (PMID 32939931, 2020).
Huntington disease (4 papers, 2015 to 2021). Huntington disease (HD) is a rare neurodegenerative disorder of the central nervous system characterized by unwanted choreatic movements, behavioral and psychiatric disturbances and dementia. "Genetic knockdown of calpain or overexpression of the calpain inhibitor calpastatin increased autophagy and improved motor signs and delayed onset of tremors in a mouse model of Huntington disease (HD)." (PMID 31936109, 2020). "Furthermore, we demonstrate that, overexpression of the calpain inhibitor, calpastatin, increases autophagosome levels and is protective in a mouse model of Huntington's disease, improving motor signs and delaying the onset of tremors." (PMID 25257175, 2015).
cardiomyopathy (3 papers, 2017 to 2025). A disease of the heart muscle or myocardium proper. "However, in addition to our cases, there have been three reports of DCM in cases with PLACK syndrome supporting an association of mutated CAST with recessive cardiomyopathy." (PMID 41300744, 2025). "For instance, CAST[F1] Taz-KO mice had severe cardiomyopathy but normal treadmill endurance, whereas WSB[F1] Taz-KO mice had significantly impaired treadmill endurance and mild, late-onset cardiomyopathy." (PMID 40326536, 2025). "In animal models, studies have supported a biologically plausible link between calpain–calpastatin system dysregulation and cardiomyopathy." (PMID 41300744, 2025). "For example, whether overexpression of calpastatin, or application of calpeptin or MDL-28170, or apocynin would allow animals to withstand HFD-induced cardiomyopathy needs to be carefully evaluated." (PMID 28887535, 2017).
gastric cancer (3 papers, 2022 to 2025). A primary or metastatic malignant neoplasm involving the stomach. "In gastric cancer, elevated CAST expression is significantly linked to reduced overall survival, suggesting its tumor-promoting potential." (PMID 40175348, 2025). "In our present study, we demonstrated that CAST is an oncogene associated with Lgr5 in gastric cancer via the WNT signaling pathway." (PMID 35625600, 2022). "CAST is a potential cancer promoter in macrophage-infiltrated gastric cancer and regulates LGR5 expression." (PMID 41194856, 2025).
hepatocellular carcinoma (3 papers, 2017 to 2023). A malignant tumor that arises from hepatocytes. "The results confirm that calpain-1 is overexpressed and calpastatin is reduced in the muscle of rats implanted with the AH-130 hepatoma, and show for the first time that the Ca2+-dependent proteolytic system is overactivated also in the C26-bearing mice." (PMID 28469577, 2017). "screened potential autoantibody-based markers for hepatocellular carcinoma (HCC) and found that the AUC of an immunodiagnostic model including 6 TAAbs (RAD23A, CAST, RUNX1T1, PAIP1, SARS, PRKCZ) were 0.835 and 0.788 in the training and validation sets, respectively." (PMID 37251926, 2023).